BMAL1 (basic helix-loop-helix ARNT like 1)
Diseases named in the same sentence as BMAL1 in open-access papers (continued):
Sharing a sentence is not in itself a finding about the gene and the disease.
osteosarcoma (continued). "In addition, we have demonstrated that the circadian clock components RORα and Bmal1 play important roles in the MLN4924 effect in osteosarcoma cells." (PMID 27602774, 2016). "Therefore, we developed a human osteosarcoma U2OS cell reporter line (U2OS-B6) stably expressing a Bmal1 promoter-driven luciferase reporter construct (Bmal1::Luc) that exhibits robust circadian oscillations in bioluminescence." (PMID 18941634, 2008). "To test our hypothesis, we chose three different commonly used cellular circadian models, i.e., mouse embryonic fibroblasts (MEF) and hypothalamic neurons (N44) along with human osteosarcoma (U2OS) cell lines with two different circadian luciferase reporters (Bmal1 and Per2)." (PMID 35813500, 2022). "In these cancer models where MYC is amplified, which represent osteosarcoma and neuroblastoma, we and others have shown that MYC suppresses or interferes with BMAL1 and disrupts molecular clock oscillation." (PMID 37639465, 2023). "In this connection, in the human osteosarcoma U2OS cell line, BMAL1 KD diminished metabolite rhythms, while CRY1 or CRY2 perturbation generally shortened/lengthened rhythms, respectively." (PMID 36183836, 2022). "To investigate the role of Bmal1 in the anti-cancer effect of MLN4924, we first examined the endogenous Bmal1 protein levels after MLN4924 (1 μM, 24 h) treatment in osteosarcoma cell lines." (PMID 27602774, 2016). "We selected the immortalized human osteosarcoma cell line U2OS to identify and characterize binding sites of the circadian transcription factor CLOCK/BMAL1 and its inhibitor CRY1 by chromatin immunoprecipitation and next generation sequencing (ChIP-seq)." (PMID 25007071, 2014). "U2-OS osteosarcoma cells, a model commonly used in studies of the human circadian rhythm in vitro, were used to establish a reporter system to evaluate transcriptional regulation of clock genes by exogenous promoters of CLOCK or BMAL1." (PMID 36551864, 2022). "Previously, a genome-wide siRNA screen was conducted in human osteosarcoma cell line U2OS to profile clock-modifying genes globally, and knockdown of Scn5a did not significantly alter circadian periodicity of the Bmal1-Luc reporter rhythm." (PMID 34206497, 2021).
atherosclerosis (25 papers, 2014 to 2025). A disease characterized by the build-up of fatty material and calcium deposition in the arterial wall resulting in partial or complete occlusion of the arterial lumen. "In several various mouse models, we found that Bmal1 deficiency significantly increased atherosclerosis." (PMID 41026540, 2025). "To clarify the role of Bmal1 in Mφ function and atherosclerosis, we used several global and myeloid-specific Bmal1-deficient mouse models." (PMID 41026540, 2025). "We have also reported that global and liver-specific Bmal1-deficient mice are prone to atherosclerosis and show diminished hepatic cholesterol efflux into bile." (PMID 41026540, 2025). "We previously demonstrated that global and hepatic-specific Bmal1 deficiency increases atherosclerosis in Apoe−/− mice." (PMID 41026540, 2025). "Others have shown that Mφ Bmal1 deficiency enhances atherosclerosis by affecting resident inflammatory Mφs and infiltrating Ly6chi monocytes." (PMID 41026540, 2025). "Myeloid-specific Bmal1-deficient mice had higher Mφ cholesterol and displayed greater atherosclerosis compared with controls." (PMID 41026540, 2025). "Bmal1 deficiency in the human carotid aggravated intracellular ROS accumulation and endothelial‐to‐mesenchymal transition through the bone morphogenetic protein‐mediated signaling, demonstrating the central role of Bmal1 loss in atherosclerosis progression." (PMID 36056774, 2022). "Mice with monocytes- and macrophages-specific Bmal1-deficiency have enhanced atherosclerosis in carotid arteries." (PMID 33445491, 2021). "In background of atherosclerosis, Bmal1 deficiency in monocytes and macrophages promotes atherosclerosis by enhancing monocyte recruitment to atherosclerotic lesions and enhanced M2 to M1 macrophage transformation." (PMID 34627306, 2021). "A role for BMAL1 in the development of atherosclerosis was recently shown where the constitutive loss of BMAL1 expression increases lesion size in genetically susceptible mice." (PMID 27168152, 2016). "To understand why Bmal1 deficiency augments atherosclerosis, we examined multiple metabolic parameters in Bmal1+/+Apoe−/− and Bmal1−/−Apoe−/− mice fed a chow diet." (PMID 27721414, 2016). "We used global and liver-specific Bmal1-deficient Apoe−/− mice to examine the role of Bmal1 in the regulation of plasma and hepatic lipids as well as development of atherosclerosis." (PMID 27721414, 2016). "We investigated the effects of Bmal1 deficiency on atherosclerosis and observed that 3–12 months old, male Bmal1−/−Apoe−/− mice had more aortic lesions compared with Bmal1+/+Apoe−/− mice." (PMID 27721414, 2016). "Here we show that Bmal1 deficiency increases hepatic lipoprotein production, cholesterol excretion to bile and atherosclerosis." (PMID 27721414, 2016). "Both Bmal1−/−Apoe−/− and L-Bmal1−/−Apoe−/− mice showed increased hyperlipidaemia and atherosclerosis compared with apoE-deficient mice." (PMID 27721414, 2016). "The atherosclerotic lesion areas were smaller in L-Bmal1−/−Apoe−/− mice indicating that Bmal1 deficiency in other tissues also contributes to atherosclerosis." (PMID 27721414, 2016). "First, we hypothesized that Bmal1-deficient aortas and Mφs would show enhanced oxLDL uptake, thereby contributing to atherosclerosis." (PMID 41026540, 2025). "We previously demonstrated that global and hepatocyte-specific Bmal1 deficiency increases plasma lipids and atherosclerosis, thus suggesting that hyperlipidemia might be a causal factor in atherosclerosis." (PMID 41026540, 2025). "We previously showed that global Bmal1 deficiency increases plasma lipids and lipoproteins and may contribute to enhanced atherosclerosis." (PMID 41026540, 2025). "Besides Bmal1 and Clock, also the clock genes Nr1d1, Cry1/2, and Rora, have been implicated in atherosclerosis." (PMID 38484032, 2024).
atherosclerosis (continued). "It has been reported that Bmal1 deficiency enhances nuclear factor kappa-B (NF-κB) signaling, oxidative stress, and inflammatory response in mice, suggesting an effect of circadian rhythms on atherosclerosis." (PMID 38807423, 2024). "Another circadian gene, brain and muscle Arnt-like protein-1 (BMAL1), plays an essential role in circadian rhythms, the loss of which can cause abnormality including aging, aberrant blood glucose level, shortened longevity, and aggravated atherosclerosis." (PMID 33557283, 2021). "Additionally, BMAL1 has been linked to the regulation of atherosclerosis, although the nature of this regulation is uncertain as data has shown BMAL1 to both attenuate and worsen atherosclerotic pathogenesis." (PMID 34858390, 2021). "Moreover, in the study of atherosclerosis, associated with infection of Porphyromonas gingivalis that causes periodontitis, circadian clock disruption enhanced atherosclerosis progression in Bmal1−/− ApoE−/− mice." (PMID 33072766, 2020). "Thus, in various mouse models, Mφ Bmal1 deficiency enhanced atherosclerosis." (PMID 41026540, 2025). "The loss of Bmal1 in macrophages could give rise to increased trafficking of Ly6chi monocytes to atherosclerotic lesions, which resulted in an increase in macrophage content and lesion size in the carotid arteries and promoted atherosclerosis." (PMID 36056774, 2022). "Moreover, myeloid Bmal1 deficiency leads to proinflammatory macrophage phenotype changes and enhances monocyte recruitment to the atherosclerotic lesion, which then aggravates atherosclerosis." (PMID 34447794, 2021). "Thus, Bmal1 deficiency increases atherosclerosis in different mouse models." (PMID 27721414, 2016). "In global Bmal1-deficient mice, both enhanced hepatic lipoprotein production and reduced cholesterol secretion to the bile might play an important role in the development of atherosclerosis." (PMID 27721414, 2016). "Thus, western diet augments atherosclerosis in liver-specific Bmal1-deficient Apoe−/− mice." (PMID 27721414, 2016). "Here, we used multiple Apoe−/− mouse models to address the role of Mφ-specific Bmal1 in atherosclerosis." (PMID 41026540, 2025). "First, we observed that transplantation of bone marrow cells from Bmal1−/− Apoe−/− mice into Apoe−/− mice significantly enhanced atherosclerosis." (PMID 41026540, 2025). "Our antecedent study has also established that intermittent fasting (IF) improves acrolein-induced atherosclerosis by regulating the expression of CLOCK/BMAL1." (PMID 40423448, 2025). "Our prior study has shown that IF improves acrolein-induced atherosclerosis by regulating the expression of CLOCK/BMAL1." (PMID 40423448, 2025). "Here, using multiple Apoe−/− mouse models of atherosclerosis, we show that Mφ Bmal1 plays an important role in atherosclerosis." (PMID 41026540, 2025). "Our previous studies have shown that acrolein, an environmental pollutant, promotes atherosclerosis by downregulating the circadian clock genes (CLOCK/BMAL1) and disrupting circadian rhythm." (PMID 40423448, 2025). "Our previous study has indicated that IF improves acrolein-induced atherosclerosis by regulating the expression of CLOCK/BMAL1." (PMID 40423448, 2025). "In mice, disruption of the circadian clock by gene targeting of the positive regulators of circadian rhythm Bmal1 and Clock accelerates atherosclerosis progression and cardiomyopathy, respectively." (PMID 41382143, 2025). "Global or liver-specific basic helix-loop-helix ARNT like 1 (Bmal1)-deficient mice show elevated assembly and secretion of an ApoB-containing very low-density lipoprotein (VLDL), thus regulating the development of atherosclerosis." (PMID 38139244, 2023). "Bmal1 downregulation promotes oxidative stress and this aggravates periodontitis-related atherosclerosis induced by Porphyromonas gingivalis." (PMID 35111358, 2022).
atherosclerosis (continued). "Global- or liver-specific Bmal1 ablation Apoe-/- mice have higher risks of hyperlipidemia and atherosclerosis, which are reversed by virus-mediated Bmal1 overexpression." (PMID 35111358, 2022). "Most downstream target genes of BMAL1 appear to be tissue specific and play differential pathophysiological roles in atherosclerosis." (PMID 33445491, 2021). "For instance, the upregulation of miR155 increases the atherosclerosis lesion size, cell apoptosis, total triglyceride and cholesterol levels by inhibiting Bmal1 expression in ApoE−/− mice." (PMID 34575881, 2021). "For instance, myeloid Bmal1 deletion in mice has been purported to worsen atherosclerosis driven by ApoE knockout by enhancing vascular inflammation." (PMID 34858390, 2021). "Firstly, global or organ-specific knockout of Bmal1 is reported to attribute to the progression of hyperlipidemia and atherosclerosis." (PMID 34447794, 2021). "In the immune system, the myeloid deletion of Bmal1 enhances the recruitment of Ly6Chi monocytes and then worsens atherosclerosis." (PMID 34575881, 2021). "Accordingly, BMAL1 regulates macrophage polarization as well as the cyclic trafficking of Ly6Chi monocytes and myeloid Bmal1 deletion increased monocyte recruitment and worsened atherosclerosis." (PMID 32849554, 2020). "For instance, BMAL1 modulates lipoprotein production and biliary cholesterol excretion, and its ablation led to hyperlipidemia and atherosclerosis." (PMID 32849554, 2020). "Although it is clear that there is a link between the circadian clock and atherosclerosis, further dissection of the importance of BMAL1 and other clock proteins in this disease is warranted." (PMID 31847894, 2019). "On the other hand, other studies suggest that deletion of Bmal1 in myeloid cells increased monocyte recruitment and atherosclerosis lesion size." (PMID 31847894, 2019). "By studying atherosclerosis in Bmal1−/−Apoe−/− and L-Bmal1−/−Apoe−/− mice we tried to learn about the contribution of hepatic Bmal1 to atherogenesis." (PMID 27721414, 2016). "Adenovirus mediated hepatic overexpression of Bmal1 in L-Bmal1−/−Apoe−/− mice reduced hyperlipidaemia and atherosclerosis." (PMID 27721414, 2016). "Since, Bmal1 and Gata4 affect both lipoprotein production and cholesterol secretion to bile, it is likely that their higher efficacy in reducing atherosclerosis compared with Shp is secondary to their effects on both these processes." (PMID 27721414, 2016). "On the basis of these knockout and overexpression studies, we conclude that hepatic Bmal1 plays a significant role in the regulation of plasma lipids and atherosclerosis." (PMID 27721414, 2016). "In this regards, it would be interesting to explore in the future the role of intestine and macrophage-specific Bmal1 on atherosclerosis." (PMID 27721414, 2016). "This is based on the observation that expression of BMAL1 or GATA4 reduced atherosclerosis to similar extents (∼75%), whereas Shp expression reduced it by ∼50%." (PMID 27721414, 2016). "The systemic effect observed in the BMAL1−/− model differed significantly from that in ApoE−/−, indicating that presumably the Bmal1−/− mice are less prone to the development of atherosclerosis compared to the dyslipidemic ApE−/− mice." (PMID 25394423, 2014). "To unravel how Mφ-Bmal1 may contribute to atherosclerosis, we measured cellular cholesterol levels in different mouse models." (PMID 41026540, 2025). "In conclusion, Mφ Bmal1 is a key regulator of the uptake of modified lipoproteins, cholesterol efflux, lysosomal cholesterol egress, and atherosclerosis and, therefore, may be a master regulator of cholesterol metabolism in Mφs." (PMID 41026540, 2025). "Restoration of Mφ Bmal1 expression or blocking of factors that decrease its activity may be effective in preventing atherosclerosis." (PMID 41026540, 2025).
atherosclerosis (continued). "While our previous studies have demonstrated that IF improves acrolein-induced atherosclerosis by regulating the expression of CLOCK/BMAL1, the relationship between ferroptosis and the circadian clock, as well as the underlying mechanisms involved, remains to be elucidated." (PMID 40423448, 2025). "In this study, we demonstrated that myeloid-specific Bmal1 deficiency did not affect circulating lipids and lipoproteins but significantly enhanced atherosclerosis in various mouse models." (PMID 41026540, 2025). "Thus, Bmal1 plays cell-specific roles in controlling cellular cholesterol metabolism and atherosclerosis." (PMID 41026540, 2025). "Thus, Mφ Bmal1 most likely regulates several processes to guard against atherosclerosis in Apoe−/− mice." (PMID 41026540, 2025). "We consequently suggest that Bmal1 protects against atherosclerosis by regulating Mφ function." (PMID 41026540, 2025). "We observed that Mφ Bmal1 deficiency enhanced atherosclerosis without affecting plasma lipoproteins." (PMID 41026540, 2025). "Whether Bmal1 deletion is constitutive or inducible adds another layer of complexity to the outcome of atherosclerosis." (PMID 38484032, 2024). "Our previous studies showed that acrolein, an environmental pollutant, exacerbated atherosclerosis by reducing CLOCK/BMAL1 levels and disrupting circadian rhythm; in contrast, intermittent fasting (IF), a dietary regimen, ameliorated acrolein-induced atherosclerosis." (PMID 38807423, 2024). "Several studies indicate a direct link between Bmal1 and atherosclerosis (AS)." (PMID 36056774, 2022). "Besides this, it has been demonstrated that Bmal1 represses the expression of Ccl2; thus, myeloid-specific Bmal1 deletion increases monocyte recruitment and worsens atherosclerosis." (PMID 34447794, 2021). "As the LysMCre/+ heterozygous mice may have their own phenotype in a dyslipidaemic background, additional experiments are warranted to definitively conclude the myeloid-specific role of Bmal1 in atherosclerosis." (PMID 34575881, 2021). "Moreover, an organ-specific knockout of Bmal1 would also lead to disordered lipid metabolism and atherosclerosis, including the liver, endothelial cells, and myeloid cells." (PMID 34447794, 2021). "In addition, deletion of Bmal1 in myeloid cells or Rev-erbα in bone marrow-derived cells increased atherosclerosis in mice, demonstrating a role of circadian clocks in the immune system in regulating atherosclerosis." (PMID 32555251, 2020). "Overexpression of Bmal1 can reduce hyperlipidemia and atherosclerosis." (PMID 31139087, 2019). "Thus, hepatic over expression of Bmal1 lowers plasma lipids, mitigates atherosclerosis and enhances biliary cholesterol secretion in L-Bmal1−/−Apoe−/− and in Bmal1fl/flApoe−/− mice." (PMID 27721414, 2016). "On the basis of these studies, we hypothesized that Bmal1 may play an important regulatory role in plasma lipid metabolism and atherosclerosis." (PMID 27721414, 2016). "Expression of SHP reduced MTP expression, plasma lipids and atherosclerosis supporting the hypothesis that Bmal1 regulates hepatic lipoprotein production by regulating Shp." (PMID 27721414, 2016). "Surprisingly, however, the inducible loss of BMAL1 expression, post-development, did not increase atherosclerosis." (PMID 27168152, 2016). "Aortic transplantation studies have shown that aortic Bmal1 contributes to atherosclerosis." (PMID 27721414, 2016). "Thus, Mφ Bmal1 regulated atherosclerosis by acting at the cellular level." (PMID 41026540, 2025). "In short summary, disruption of the circadian clock at different nodes (BMAL1, CLOCK, CRYs, PERs, and REV-ERB) promotes atherosclerosis." (PMID 33445491, 2021).
atherosclerosis (continued). "Hepatic overexpression of Bmal1 in liver-specific Bmal1-/- knockout and APOE-/- knockout mice can reduce hyperlipidemia and atherosclerosis." (PMID 31139087, 2019). "By contrast, global and liver-specific Bmal1-/- knockout and APOE-/- knockout mice show increased hyperlipidemia and atherosclerosis." (PMID 31139087, 2019). "However, our studies involving overexpression of BMAL1, SHP or GATA4 in L-Bmal1−/−Apoe−/− mice indicate that a combination of hepatic lipoprotein over production and reduced biliary cholesterol excretion might contribute additively to atherosclerosis." (PMID 27721414, 2016). "Transplantation of arteries from Bmal1-knockout mice to wild type mice leads to the development of atherosclerosis in the transplanted blood vessels without affecting the systemic hemodynamics." (PMID 33445491, 2021). "Thus, hepatic Bmal1 regulates at least two pathways (VLDL production and cholesterol efflux to bile) and disruptions in these pathways increase plasma lipids and atherosclerosis." (PMID 27721414, 2016). "However, whether melatonin alleviates atherosclerosis through CLOCK and BMAL1 regulation is unknown." (PMID 33557283, 2021).